CXADRP3 (CXADR pseudogene 3)
Gene: Transcribed processed pseudogene on chromosome 18 (14,478,168 to 14,479,267, reverse strand). Ensembl gene ENSG00000265766.
Diseases named in the same sentence as CXADRP3 in open-access papers:
CXADRP3 is named in the same sentence as 1 disease in open-access papers, as found by Europe PMC text mining. Sharing a sentence is not in itself a finding about the gene and the disease.
CXADRP3 shares sentences with these, for which no sentence is quoted: cancer (1 paper).